HLA-C (major histocompatibility complex, class I, C)
Diseases named in the same sentence as HLA-C in open-access papers (continued):
Sharing a sentence is not in itself a finding about the gene and the disease.
hepatitis C (7 papers, 2011 to 2024). "Nevertheless, HLA-C-restricted viral peptides have been implicated during disease progression in HIV and hepatitis C infections." (PMID 39337964, 2024). "In the context of hepatitis C virus infections, where HLA-C1/C1 haplotype carriers homozygous for KIR2DL3 have a higher probability of resolution, certain HLA-C alleles are now emerging as particularly beneficial." (PMID 21665273, 2011). "For example, CNV of KIR3DL1/S1 influences HIV control and expression differences of KIR2DL3, interacting with HLA-C, may have a profound effect on resolution of hepatitis C virus infection." (PMID 33632228, 2021). "Vijayaprakash Suppiah and colleagues show that genotyping hepatitis C patients for the IL28B, HLA-C, and KIR genes improves the ability to predict whether or not patients will respond to antiviral treatment." (PMID 21931540, 2011).
hepatocellular carcinoma (7 papers, 2013 to 2025). A malignant tumor that arises from hepatocytes. "In previous research of our team, HLA-A*01 and B*57 alleles were significantly associated with chronic HBV complications such as cirrhosis and hepatocellular carcinoma (HBV-HCC) while the HLA-C*15 allele was linked with protection against HBV persistence complications." (PMID 40284905, 2025). "KIR/HLA-C combinations also influence the development of HCV related hepatocellular carcinoma (HCC)." (PMID 34831331, 2021).
Infertility (7 papers, 2021 to 2024). "Summarized effect of ERAP, HLA-C, and KIR combined polymorphisms on the susceptibility to infertility and recurrent implantation failure." (PMID 34745129, 2021). "The implications of HLA-C alleles, in association with KIR receptor variants, in infertility or fertility problems has become a reason for genetic testing in patient couples, with recommendations from geneticists, gynecologists, and fertility of FIV specialists." (PMID 39201523, 2024). "We then narrowed our focus to patients without OAPS as the primary cause of recurrent infertility, aiming to minimize confounding factors associated with maternofetal HLA-C-KIR mismatch." (PMID 38336826, 2024). "A Polish study in a group of 1064 men examined which potential KIR and HLA-C genes/receptors and their combinations may affect infertility, and whether KIR and HLA-C genes affect sperm parameters." (PMID 38201263, 2023). "This review discusses the immunogenetic causes of infertility related to KIR (killer immunoglobulin-like receptor) and HLA-C antigens (human leukocyte antigen), whose interactions may affect the course of a pregnancy." (PMID 38201263, 2023). "This study shows for the first time that some genetic combinations of ERAP, KIR, HLA-C in women and their partners may predispose to RIF and infertility." (PMID 36293373, 2022). "Some of the combinations of the ERAP, KIR, and HLA-C genes and their association with infertility and RIF need to be discussed, as there is no published research to date on the effect of such complex variants on reproductive success." (PMID 34745129, 2021).
inflammatory bowel disease (7 papers, 2018 to 2025). A spectrum of small and large bowel inflammatory diseases of unknown etiology. "HLA‐C has been associated with several disease susceptibility genes, including inflammatory arthropathy, chronic obstructive pulmonary disease, inflammatory bowel disease, and so on." (PMID 40657813, 2025). "High HLA-C levels have been related to the risk of suffering from inflammatory bowel disease or spondyloarthropathy." (PMID 37240048, 2023). "Higher levels of HLA-C protein are related to risk of suffering inflammatory bowel disease (IBD)." (PMID 35159323, 2022). "HLA-C has also been related to inflammatory bowel disease (IBD) risk in the Japanese." (PMID 32709981, 2020).
sarcoma (7 papers, 2011 to 2025). A usually aggressive malignant neoplasm of the soft tissue or bone. "Importantly, 14 genes involved in the interferon gamma response were upregulated including HLA-B, HLA-C, PD-L1, IL2RB and TNFAIP6, suggesting the reprogramming of the immune microenvironment of sarcoma cells on chidamide inhibition." (PMID 33637599, 2021).
pregnancy disorder (6 papers, 2011 to 2024). A disorder that is related to pregnancy. "HLA-C variants have been implicated in pregnancy disorders, including pre-eclampsia and high birthweights, via the uNK allorecognition system." (PMID 39019884, 2024). "Genetic studies of large pregnancy cohorts suggest that women with a KIR AA genotype are at increased risk of pregnancy disorders when the foetus has an HLA-C allele carrying a C2 epitope (C2+HLA-C)." (PMID 34234770, 2021). "Although our initial genetic studies have revealed that particular combinations of NKR KIR and MHC HLA-C genotypes are associated with an increased risk of pregnancy disorders, much further work at both genetic and functional levels is required before these findings can be translated to the clinic." (PMID 21665273, 2011). "KIR2DL1 is also critical to our model of pregnancy disorders, as it is strongly inhibitory for HLA-C allotypes bearing C2 epitopes." (PMID 27815424, 2016). "There is an increased risk of pregnancy disorders with certain inhibitory maternal KIR and fetal HLA-C combinations." (PMID 27815424, 2016).
thymoma (6 papers, 2001 to 2025). A neoplasm arising from the epithelial cells of the thymus. "Among non-thymoma patients (n=14), the frequency of HLA-DQB1 03:03 (25% vs 15.9%, P = 0.195), HLA-C 01:02 (25% vs 15.9%, P = 0.195), HLA-B*52:01 (7.1% vs 3%, P = 0.669) was higher than that in the normal population, the difference was also not statistically significant." (PMID 41357573, 2025). "Among thymoma patients (n=9), the frequency of HLA-DQB1 03:03 (33.3% vs 15.9%, P = 0.057), HLA-C 01:02 (27.8% vs 15.9%, P = 0.167), HLA-B*52:01 (5.6% vs 3%, P = 1.0) was higher than that in the normal population, but the difference was not statistically significant." (PMID 41357573, 2025).
chronic hepatitis C (5 papers, 2011 to 2021). "The factors analyzed in our previous study using conventional univariate and multivariate analysis showed that there was a strong association between IFNL3, HLA-B*44, KIR3DS1, and HLA-C*12 and the probability of developing chronic hepatitis C." (PMID 33624609, 2021). "The frequency of the KIR2DL2 and KIR2DL2 plus HLA-C was found higher in chronic hepatitis C patients than in control group." (PMID 26206121, 2016). "In particular, the capability of KIR2DS2 to directly recognize peptides from HCV helicase presented by HLA-C*01:02 (an HLA-C C1 allotype) may explain, at least in part, the protective effect of this aKIR in chronic hepatitis C infection." (PMID 31231370, 2019). "In our previous study, we proposed a simple tool for the prediction of spontaneous resolution and chronic hepatitis C based on IFNL3 genotype and genetic profiles (GUP/GFP) using a combination of HLA-B, HLA-C, and KIR genes." (PMID 33624609, 2021).
Hashimoto thyroiditis (5 papers, 2008 to 2023). An autoimmune disorder caused by the production of autoantibodies against thyroid tissue. "Neither HLA-C nor HLA-B*27 alleles have been implicated in the development of Hashimoto's thyroiditis; thus, evidence regarding an HLA link for psoriasis with Hashimoto's thyroiditis has not been fully elucidated." (PMID 33585138, 2021).
Hepatitis (5 papers, 2013 to 2022). Inflammation of the liver. "Interestingly, HLA-C*07:01 has also been associated with the response to peg-interferon alfa-2b and ribavirin therapy in hepatitis C33." (PMID 32066683, 2020). "A positive correlation between IRAE and homozygosity was found for HLA-A and HLA-C homozygosity for colitis, and HLA-A, HLA-B, and HLA-C homozygosity for hepatitis." (PMID 35053465, 2022). "KIR/HLA-C signaling pathway influences the innate immune response which is the first defense to hepatitis C virus (HCV) infection." (PMID 34220799, 2021).
Hypertension (5 papers, 2021 to 2026). The presence of chronic increased pressure in the systemic arterial system. "HLA-C*06:02-positive status is often associated with lower central adiposity, lower incidence of hypertension, and a lower prevalence of other cardiometabolic comorbidities." (PMID 39261909, 2024). "This indicates that the HLA-C*06:02 allele contributed the greatest effect in protecting against high blood pressure." (PMID 39261909, 2024). "Like PRS-HLA, HLA-C*06:02 was found to be protective against high blood pressure mainly in the European cohort." (PMID 39261909, 2024). "This was consistent with one of our HLA-C*06:02 results, which was found to be protective against high blood pressure." (PMID 39261909, 2024).
metastatic melanoma (5 papers, 2015 to 2023). A melanoma that has spread from its primary site to another anatomic site. "In addition, the Kaplan-Meier survival analysis further revealed that the high-expression groups of HLA-C, HLA-E, and HLA-F had a longer survival time among patients with metastatic melanoma." (PMID 37435067, 2023).
Miscarriage (5 papers, 2016 to 2022). A pregnancy that ends at a stage in which the fetus is incapable of surviving on its own, defined as the spontaneous loss of a fetus before the 22th week of pregnancy. "Further, specific dNK-trophoblast interactions through dNK KIR and fetal EVT HLA-C are of particular importance, as certain KIR–HLA-C combinations have been associated with an increased risk of pre-eclampsia, recurrent miscarriage and IUGR." (PMID 35832424, 2022). "Alloreactivity and differences thereof by these virus-specific CD8+ T cells, obtained after normal pregnancy and miscarriage cases, against target cells expressing allo-HLA-C, -E, and -G molecules can then be investigated." (PMID 30574149, 2018). "For each of these quintiles, we plotted the percentage of immunogenic antigens, and we investigated in which quintile the single immunogenic HLA-C*01:02 of secundigravidae with a prior miscarriage was present." (PMID 27999574, 2016). "Therefore, one could hypothesize that the single immunogenic HLA-C*01:02 in the secundigravidae with prior miscarriage group has a higher number of PIRCHE-II compared to the other non-immunogenic HLA." (PMID 27999574, 2016).
myocarditis (5 papers, 2019 to 2025). Myocarditis is a condition that is characterized by inflammation of the heart muscle (myocardium). "HLA class I allele HLA-C*07:01 (OR = 2.89, 95% CI: 1.11–7.53; P = 0.03) and HLA class II allele HLA-DMB*01:01 (OR = 3.22, 95% CI: 1.158.97; P = 0.026) were associated with increased odds for myocarditis." (PMID 32066683, 2020). "Among the 14 patients with MG combined with myositis and myocarditis, the frequencies ofHLA-DQB1*03:03 and HLA-C*01:02 loci were higher than those in the normal population." (PMID 41357573, 2025).
ovarian carcinoma (5 papers, 2020 to 2025). A malignant neoplasm originating from the surface ovarian epithelium. "We also demonstrated the in vitro and in vivo efficacies of pNK cells against cisplatin-resistant A2780cis ovarian cancer cells having a high programmed death-ligand 1(PD-L1) and low HLA-C expression." (PMID 34686187, 2021). "Taken together, these data suggest that the growth of ovarian cancer cells resistant to cisplatin was significantly inhibited by pNK treatment and this effect could be related to the low HLA-C expression in the cisplatin-resistant cells." (PMID 34686187, 2021).
ZIKV infection (5 papers, 2020 to 2025). "ZIKV infection causes endoplasmic reticulum stress in trophoblasts, leading to down-regulation of HLA-C and HLA-G." (PMID 40358173, 2025). "During acute ZIKV infection, circulating PMBCs had increased expression of HLA-C and HLA-E, suggesting a potential for NK cell inhibition, similar to what we found in acute DENV." (PMID 41000887, 2025). "We found that increased expression of NK inhibitory receptors HLA class I (Pan-HLA; HLA-C, HLA-E) and CD95 (Fas) are predictive of acute ZIKV infection vs. healthy across multiple cell types." (PMID 41000887, 2025). "Interestingly, HLA-C is one of only 25 genes significantly upregulated in NPCs from CZS-affected patients compared to their unaffected dizygotic twin; possibly indicating HLA-I involvement in CZS development following congenital ZIKV infection." (PMID 41166287, 2025).
Chagas disease (4 papers, 2013 to 2021). A parasitic infection caused by Trypanosoma cruzi. "This study also showed that the MICA*008~HLA-C*06 haplotype was a risk factor for digestive form of Chagas disease." (PMID 34489964, 2021).
chronic GVHD (4 papers, 2006 to 2021). "Similarly, HLA-C locus mismatches slightly increased hazard of chronic GVHD with a borderline significance (HR, 1.13; 95% CI, 1.01 to 1.27; P = .047; I2 = 67.2%)." (PMID 28206973, 2017). "Similarly, HLA-C locus mismatches had a trend of reduced risk of relapse, but had a significant increased risk of TRM and mortality and a slightly increased risk of chronic GVHD." (PMID 28206973, 2017).
chronic hepatitis B (4 papers, 2012 to 2025). "A recent study analyzed whether HLA-C and KIR genotypes were associated with treatment outcome for chronic hepatitis B infection (CHB) showing that the combination of KIR2DL1 with its ligand HLA-C2 is predictive of clinical outcome of infection predicted." (PMID 29707126, 2018). "This study aims to further screen the T-cell epitopes restricted by 15 prevalent HLA-B and 14 prevalent HLA-C allotypes and establish a universal assay for counting reactive HBV-specific T cells in patients with chronic hepatitis B (CHB)." (PMID 41583498, 2025).
Cirrhosis (4 papers, 2011 to 2025). A chronic disorder of the liver in which liver tissue becomes scarred and is partially replaced by regenerative nodules and fibrotic tissue resulting in loss of liver function. "HLA-C showed an association with sex, alcohol consumption, cirrhosis with p values = 0.001, 0.045, 0.043 respectively." (PMID 34834481, 2021).
fetal growth restriction (4 papers, 2011 to 2023). A fetus that does not grow beyond the 10th percentile of conventionally accepted weight for gestational age. "Expression of these specific receptors by uNK cells suggests that they interact with EVT, and specific KIR/HLA-C combinations have been associated with pregnancy complications, including pre-eclampsia, fetal growth restriction, and recurrent miscarriage." (PMID 31316752, 2019). "Pre-eclampsia, fetal growth restriction, and recurrent pregnancy failure have been associated with altered uNK cell numbers and function and specific KIR/HLA-C combinations but the significance of these observations is not fully established." (PMID 31316752, 2019). "Maternal dNK KIR and HLA-C interaction has an effect on birth weight, particularly the paternal HLA-C, and correlates with pre-eclampsia and fetal growth restriction." (PMID 31057536, 2019).
metastatic tumor (4 papers, 2021 to 2025). "There is a significant reduction in the expression of the antigen presenting genes B2M, HLA-A, HLA-B, and HLA-C in the recurrent/metastatic tumors relative to the primary tumors." (PMID 33796222, 2021).
plague (4 papers, 2012 to 2023). Plague is a severe bacterial infection caused by the gram-negative bacterium Yersinia pestis. "We also observed differences in HLA-C*06 and DRB1*13 between the plague victims and modern Germany, but these were not statistically significant." (PMID 34002224, 2021).
psoriasis vulgaris (4 papers, 2006 to 2024). Plaque psoriasis is the most common presentation of psoriasis. "One hundred forty-seven unrelated Slovak patients with psoriasis vulgaris (average age at onset 28 ± 14 years) were genotyped for the HLA-C, DQB1 and DRB1 alleles by the polymerase chain reaction using sequence-specific primers." (PMID 23184486, 2013). "Susceptibility to psoriasis vulgaris in our study group is significantly associated with HLA-C*06 (odds ratio (OR) = 3.85), DRB1*07 (OR = 2.56) and DQB1*02 (OR = 1.09), respectively, whereas DRB*01 (OR = 0.05) is associated negatively." (PMID 23184486, 2013). "The HLA-C locus profile of this cohort was studied by methods based on molecular biology and was compared with that of 45 patients with psoriasis vulgaris and 177 healthy blood donors from the same ethnic origin." (PMID 17166285, 2006). "For example, they are all associated with class I MHC alleles, while studies found that HLA-C*06 is a major risk factor for psoriasis vulgaris but not for PsA." (PMID 39335643, 2024).
respiratory failure (4 papers, 2008 to 2024). The significant impairment of gas exchange within the lungs resulting in hypoxia, hypercarbia, or both, to the extent that organ tissue perfusion is severely compromised. "Epigenome-wide association studies implicate differential CpG methylation of the HLA-C locus in conferring risk for developing severe infection with respiratory failure." (PMID 39337964, 2024).
sacroiliitis (4 papers, 2019 to 2025). "The HLA-B*27:05:02 allele is positively associated with enthesitis, dactylitis, and symmetric sacroiliitis, while the HLA-B*08:01:01 and HLA-C*07:01:01 haplotype is associated with joint fusion and deformities, asymmetric sacroiliitis, and dactylitis." (PMID 40284188, 2025). "For example, B*08, B*27, and B*38 can induce PsA development, whereas HLA-B*27:05:02 is associated with arthritis, enthesites, dactylites, and symmetric sacroiliitis, and HLA-B*08:01:01 and HLA-C*07:01:01 are associated with erosive arthritis, dactylites, and asymmetric sacroiliitis." (PMID 37238999, 2023).
uveitis (4 papers, 2020 to 2024). An inflammatory process affecting a part of or the entire uvea. "The frequency of HLA-C*01, HLA-DRB1 *04:05, and HLA-DQB1*04:01 was significantly higher in cases with VKH-like uveitis (P = 0.029)." (PMID 37604934, 2023).
acute leukemia (3 papers, 2013 to 2026). A clonal (malignant) hematopoietic disorder with an acute onset, affecting the bone marrow and the peripheral blood. "This fact, however, seems less likely given that the negative effect of the KIR2DL1/HLA-C*04 interaction was observed in different lineages of acute leukemia, lymphoblastic (B and T), and myeloblastic." (PMID 34064810, 2021).
atherosclerosis (3 papers, 2023 to 2024). A disease characterized by the build-up of fatty material and calcium deposition in the arterial wall resulting in partial or complete occlusion of the arterial lumen. "Within MHC-I, alleles for HLA-B*13:02 and HLA-C*06:02 were associated with a higher atherosclerotic burden while HLA-B*38:01 was associated with less atherosclerosis when researchers adjusted for other cardiovascular risk factors in patients with psoriatic disease." (PMID 37681883, 2023).
autoimmune hepatitis (3 papers, 2015 to 2024). Hepatitis caused by autoantibodies. "Another study in a European population showed that the HLA-C*07:01 allele generates susceptibility to autoimmune hepatitis (AIH)." (PMID 39599823, 2024).
brain cancer (3 papers, 2013 to 2023). A primary or metastatic malignant neoplasm affecting the brain. "We found that immunogenicity varied widely across HLA alleles with HLA-C alleles exhibiting the highest immunogenicity, and that immunogenicity scores were negatively associated with the population-based HLA-brain cancer profile, particularly for JCV, HHV6A, HHV5, HHV3, HHV8, and HHV7." (PMID 38057480, 2023).
cervical disease (3 papers, 2012 to 2022). "Previously published studies linked specific HLA-C variants to HPV-related cervical disease to patients chronically infected by HCV and by HBV." (PMID 36499177, 2022). "In Korean women, HLA-C is associated with HPV-cervical disease: HLA-C∗03:03 confers susceptibility whereas HLA-C∗01 has a protective effect." (PMID 23936772, 2013). "This was positively correlated with the downregulation of corresponding gene transcription, in addition to HLA-A, HLA-B and HLA-C genes coding for HLA-I, in fresh cervical lesions detected by semi-quantitative RT-PCR." (PMID 23024775, 2012).